CD44 (CD44 molecule (IN blood group))
Diseases named in the same sentence as CD44 in open-access papers (continued):
Sharing a sentence is not in itself a finding about the gene and the disease.
tumor (continued). "Interestingly, these immunosuppressive protein markers were also significantly (* p < 0.05) correlated with an increased expression of certain tumor markers, such as CD44, B2M, HER2/ErbB2, S6, B7-H3, ER alpha and S100B." (PMID 34944780, 2021). "Interestingly, triple therapy increased CD8+ CD44+/Treg ratio by both augmenting tumor-infiltrating CD8+ CD44+ T cells and diminishing Tregs proportions." (PMID 33688020, 2021). "This may be attributed to the enhanced accumulation of NPs at the tumor and redox- and pH-responsive targeting within tumor cells via HA and CD44." (PMID 34162396, 2021). "Interestingly, almost all recurrent human PDAC tumor cells became CD44+ following a standard chemotherapy for PDAC." (PMID 34349642, 2021). "BRO reduced CD44 expression from the surface of tumor cells." (PMID 33921242, 2021). "CD44 is a common biomarker of cancer stem cells as well as tumor cell invasion and metastasis." (PMID 34178024, 2021). "However, the matched recurrent tumor samples did exhibit a strong positive correlation between CD44 and both CLDN4 and CLDN7 (Pearson correlation, R= 0.58, p= 0.002 and R= 0.61, p= 0.01, respectively)." (PMID 33828978, 2021). "In summary, overexpression of the GSK3β, β-Catenin, STAT3, and CD44 oncogenes and downregulation of the miR-135b tumor suppressor in GBM tumor samples compared to adjacent normal tissue were associated with poor patient prognoses, stemness, and therapeutic resistance." (PMID 33671112, 2021). "The mice were injected intravenously, and the long-term anti-tumor immunity results showed that after 30 d of treatment, the proportion of T cells (CD45+CD3+CD44+) in lymph nodes of mice was about six times higher than that of tumor-bearing mice and healthy mice after 1 d of treatment." (PMID 34596000, 2021). "However, the expression of XBP1s, CXCR4, and CD44 was much higher in APVT tumor cells of PCNSL than those in the control tissues, which were negative except for very weak positive for CD44." (PMID 34093792, 2021). "In the tumor microenvironment, hypoxia regulates CD44 expression and CD44H cell homeostasis." (PMID 34680112, 2021). "Eno1 was enriched in CM and its interaction with CD44 was involved in Eno1's anti-tumor action." (PMID 34373756, 2021). "Further analysis of these CD8+ T-cells revealed that there were reduced terminally-differentiated PD-1+CD44+Tim3+TCF1−CD8+ T-cells but significantly increased stem-like PD-1+CD44+Tim3−TCF1+CD8+ T-cells in the tumor of Prdm1fl/flFoxp3YFP-Cre mice compared to WT mice." (PMID 34798898, 2021). "The molecular surface markers CD44 and EpCAM were determined to identify whether it was a tumor stem cell." (PMID 34239355, 2021). "In contrast, SCCA1/2‐ and CD44‐positive cells were preferentially located in the tumor core." (PMID 34115931, 2021). "A DMR was also identified in the BCL9L gene—an activator of Wnt signaling associated with B cell malignancies that have been implicated in cancer development and epithelial-mesenchymal transition through a down-regulation of c-Myc, cyclin D1, CD44, and vascular growth factor in tumor cells." (PMID 34502260, 2021). "However, it seems that larger analyses demonstrate that increased CD44 expression has an unlimited correlation with higher histological tumour grade and an advanced clinical tumour stage." (PMID 34944493, 2021). "The stem cell marker CD44 was detectable both in serum sample and tumor tissue of SCLC patients." (PMID 34187156, 2021). "As few as 100 CD44+ cells are sufficient to initiate tumour formation in nude mice." (PMID 34884696, 2021). "Finally, we confirmed the effect of MDA-MB-231, RT-R-MDA-MB-231, and CD24−/low/CD44+ cells on tumor progression in an in vivo xenograft model in mice." (PMID 34502547, 2021). "Furthermore, several studies have demonstrated that HIF-2α is preferentially expressed within a tumor stem cell subpopulation, stimulated by CD44 and that it drives tumor differentiation." (PMID 33673417, 2021).
tumor (continued). "Furthermore, the expression of miR-30c in CD44+ CSCs was lower compared to that of CD44- tumor cells in TNBC PDX models, suggesting a possible negative regulation between CD44 and miR-30c." (PMID 33995681, 2021). "Importantly, the partial silencing of CD44 in EO771 tumor cells reduced the inhibitory effect of recombinant Eno1 proteins on the MTT-based viability, and partially suppressed the Eno1-driven downregulation of Lrp5, Runx2, and TGFβ in EO771 tumor cells." (PMID 34830748, 2021). "As a primary ligand of CD44, HA increases the stability and safety of rGO by enhancing the tumor-targeted distribution of DOX to CD44-overexpressing cancer cells, thereby providing better drug accumulation and substantial reduction of tumor volume from in vivo study in nude mice." (PMID 33804239, 2021). "ITGB1 (also known as CD29) and CD44 are reported as tumor stem cell markers, and the presence of tumor stem cells could affect the drug treatment and subsequent tumor recurrence." (PMID 38650282, 2021). "The physiological functions of CD44 indicate that it is involved in the metastasis of tumours." (PMID 34944493, 2021). "Furthermore, the combined treatment reduced the proportion of CD133+CD44+ tumor cells than either sorafenib alone or 3-HAA alone." (PMID 34230478, 2021). "Targeting CD44 isoforms may reverse some malignant behaviours and sensitise tumour cells to therapy." (PMID 34944493, 2021). "Previously we observed CD44 in human HNSCC tumor tissue samples by immunofluorescence." (PMID 34307351, 2021). "The authors also confirmed that after further HA modification, the obtained nanocomposites could target CD44-overexpressing cancer cells and achieve drug release mediated by HAase, further leading to enhanced tumor elimination." (PMID 34041494, 2021). "For furthermore analysis, we utilized The Cancer Genome Atlas (TCGA) public database and identified GSK3β, β-Catenin, STAT3, and CD44 oncogenes to be overexpressed in GBM tumor samples compared to adjacent normal tissue groups, and this was associated with poor cancer prognoses." (PMID 33671112, 2021). "Additionally, CD44-targeted, mAb-modified Doxil mice demonstrated a higher doxorubicin concentration inside the tumour cells compared to Doxil-treated mice." (PMID 34944493, 2021). "CD44 is a transmembrane glycoprotein expressed in several healthy and tumor tissues." (PMID 33505471, 2021). "Since the overexpression of the HA receptor (CD44) is important to enhance the uptake of the HA-functionalized CNTs through receptor-mediated endocytosis, we analyzed the expression of this membrane receptor in the tumor and non-tumor cells." (PMID 34209588, 2021). "CD44 helps promote invasion and angiogenesis of tumor cells." (PMID 33672684, 2021). "Then, we examined the properties of CD24−/low/CD44+ cells related to tumor progression by comparing MDA-MB-231 cells and RT-R-MDA-MB-231 cells harboring different proportions of CD24−/low/CD44+ cells with the CD24−/low/CD44+ cells isolated from RT-R-MDA-MB-231 cells." (PMID 34502547, 2021). "Taken together, these observations support the notion that CD44 ICD has a tumor promoting role." (PMID 33804427, 2021). "HA, a major extracellular matrix component, is a physiological ligand that is overexpressed in CD44 on the surface of malignant tumor cells and can be used to selectively activate multiple oncogenic signaling pathways that lead to tumor cell-specific phenotypes." (PMID 34575403, 2021). "Moreover, CD44 is considered to be a major marker for stem‐like cells in several types of tumours (Zöller, 2011)." (PMID 33210459, 2021). "The aptamer selectively binds to CD44-expressing tumor cells." (PMID 35431911, 2021).
tumor (continued). "While both the 2-D and 3-D culturing systems allowed for the maintenance of the GSC biomarkers, CD133 and CD44, we selected to conduct our studies using the 3-D culturing system as such systems are more representative of the parental tumour, especially in terms of treatment resistance." (PMID 34066147, 2021). "Similarly, the DFS of patients with a high frequency of CD44-/CD24- tumor cells or CD44+/CD24- CSCs was significantly shorter than those with a low frequency of corresponding cells." (PMID 34318746, 2021). "A less favorable CD44+CD8+ T cell to total MDSC ratio within the tumor microenvironment may contribute to the impairment in CD8+ T cell effector function we observed within the tumor microenvironment." (PMID 34064933, 2021). "Six-week-old female BALB/c nude mice were injected subcutaneously with MDA-MB-231, RT-R-MDA-MB-231, and CD24−/low/CD44+ cells, and tumor volumes and body weights were measured three times weekly beginning on the 7th day after injection, as described in the Materials and Methods section." (PMID 34502547, 2021). "Interestingly the tumor growth of CD44+CD133+ was faster in secondary xenografts than in primary transplants." (PMID 33994850, 2021). "HA specifically binds to the CD44 cell surface marker that is overexpressed in some tumours." (PMID 34834022, 2021). "Strongly CD44-positive CAFs are particularly frequent in tumor hypoxic areas." (PMID 34073987, 2021). "The experimental conditions for surface modification were optimized in vitro, and the targeting ability of PHA‐EVs after intravenous injection was examined using a noninvasive optical imaging technique for animal models with CD44‐involving diseases such as RA and tumour." (PMID 33738083, 2021). "However, CD44 expression on tumor cells in vivo (primary tumor) was significantly increased compared to cell culture cells." (PMID 34070094, 2021). "They reported that CD44 overexpressed by CSCs could induce the macrophages in the TME to secrete the cytokine osteopontin that can in turn bind to CD44 on the surface of tumor cells, thereby promoting tumor cell subclone formation." (PMID 34262865, 2021). "After initiating therapy, only 20.6% of the malignant epithelia in BX2 were Ki67+ while the proportion of CD44+ cells remained similar at 14%, which may indicate a global tumor response to PARP inhibition but less effect on the proliferative stem population." (PMID 34211050, 2021). "Moreover, patients in the C1 group, with a low frequency of CSCs and higher frequency of CD44-/CD24- tumor cells, also had a worse DFS than those with a lower frequency of CD44-/CD24- tumor cells in the C0 group." (PMID 34318746, 2021). "For PDAC, the expression of ADAM17 (p = 0.008, IHC-score 3.43 vs. 1.73), CD44 (p = 0.012, IHC-score 3.64 vs. 2.27), Notch1 (p = 0.012, IHC-score 2.21 vs. 0.64), and Notch4 (p = 0.008, IHC-score 2.86 vs. 0.91) was significantly higher in the tumor tissue." (PMID 33498866, 2021). "After miRNA‐34 mimics encapsulated in liposomal carriers had been systemically delivered in an orthotopic model of pancreatic cancer using MiaPaca‐2 cells, tumour growth and CD44+ cell counts decreased while tumour cell apoptosis increased, suggesting a decline in metastatic cells." (PMID 33314500, 2021). "Single-walled carbon nanotubes conjugated to CD44 antibodies with salinomycin and paclitaxel could target and eradicate both whole tumor cells and CSC populations." (PMID 34381705, 2021). "The majority of Tag-Th1 cells in the tumor and PLN expressed the lymphocyte activation-associated membranous antigen CD69 independent of TBI, were further classified as effector memory T cells (CD44+CD62L-) and stained positive for the immune checkpoint PD-1." (PMID 34335959, 2021).
tumor (continued). "In the context of PDAC, our group has demonstrated that low-dose PDT followed by chemotherapy significantly reduces stem-like tumor cell populations that are known to contribute to treatment resistance and metastatic potential, in part through the downregulation of CD44 and CXCR4." (PMID 34830934, 2021). "Additionally, CD44 promotes PD-L1 expression and its tumor-intrinsic function in both breast and lung malignancies." (PMID 34503301, 2021). "We could not detect an overexpression of MSI in the analyzed tumors, but we did show a significant overexpression of CD44 in all three tumor entities." (PMID 33498866, 2021). "Importantly, Eno1 immunoprecipitated CD44, a cell-surface adhesion receptor, and its silencing suppressed Eno1-driven tumor inhibition." (PMID 34373756, 2021). "Abnormal activation of the Wnt/β-catenin pathway has been found to play an important role in the occurrence and development of tumors, and its pathway-related factors cyclin D1, c-jun, CD44, and c-Met are considered to be effective oncogenes in tumor progression." (PMID 34426559, 2021). "CD44 is also regulated by a different class of non-coding RNA molecules known as the circular RNAs (circRNAs), single-stranded RNAs identified in malignant tumour cells which can join the 3′ end to the 5′ end of the RNA molecule." (PMID 34944493, 2021). "The proteolytic cleavage of CD44 is required for the migration of tumor cells." (PMID 33450869, 2021). "Additionally, the overexpression of PLK1 in tumor cells was shown to activate cancer stem cells (CSCs), with the cluster of differentiation 44 (CD44) surface marker mostly being expressed." (PMID 34063946, 2021). "In addition, the HPA data of CCND1, PLK1, and CD44 expression in tumor smaples exhibited high staining intensities, and all the IHC images were obtained from the HPA database to validate the expression of genes in the cancer types at the protein level." (PMID 34063946, 2021). "In addition to HE-stained sections, tumor cells were highlighted using immunohistochemical staining of neoplastic cells with a CD44 antibody." (PMID 33808256, 2021). "The thermosensitive dual targeted H_Np was rapidly up taken by 4T1 tumor cells due to its high binding affinity of CD44 towards HA with 1.6-fold tumor accumulation, 10-fold tumor growth inhibition activity, and 10-fold angiogenesis as compared to non-targeted preparation." (PMID 35431911, 2021). "Immunoprecipitation revealed that extracellular Hsp90ab1 interacted with latent TGFβ (LAP-TGFβ) as an inhibitor of TGFβ activation, while Hsp90ab1 and Eno1 interacted and suppressed tumor progression via CD44, a cell-adhesion receptor and a cancer stem cell marker." (PMID 34830748, 2021). "It is well known that M2 TAMs accelerate tumor cell invasion and angiogenesis and suppress antitumor immunity, which explains why CD44 can be prognostic biomarker and confirms immunity function of CD44." (PMID 35187044, 2021). "Notably, high levels of PrPC expression identify a functionally distinct subpopulation of CD44-positive CCSCs which displays greater tumor-initiating and metastatic potential than PrPC-negative ones." (PMID 33418999, 2021). "In the process of tumor cell dormancy, DTCs may retain stem-like properties such as quiescence, with the increased expression of stem cell markers CD44, SOX2, CD133, or Lgr528,29." (PMID 33986252, 2021). "Recently, CD44 has been identified as a tumor-initiating CSC marker in various cancers." (PMID 34949193, 2021). "In addition, we found that the SPP1/CD44 signaling plays important roles in the induction of MES-like tumor cells." (PMID 34805184, 2021). "Despite the impairment in DC cytotoxicity, there is evidence that stimulating them with CSC CD44+ lysates generates an anti-tumor phenotype of dendritic cells, which in turn stimulates the cytotoxic activity of lymphocytes, decreasing tumor size and increasing survival in murine models." (PMID 34503571, 2021).
tumor (continued). "Another experiment identified a role for IGFBP3 in the growth of oesophageal squamous cell carcinoma cells with high CD44 expression by suppressing ROS production through an IGF-independent mechanism in the hypoxic tumour microenvironment and ultimately exerts tumour-promoting activities 37,38." (PMID 34512163, 2021). "CD44-overexpressing cells comprised not only tumor cells and cancer stem cells, but also CAFs." (PMID 34073987, 2021). "In addition, GBMs expressing high CD44 in the tumor periphery show enhanced expression of CD44 by inhibition of VEGF with Bev, leading to more invasive and aggressive tumors, and resulting in earlier progression and worse prognosis." (PMID 33543833, 2021). "Since we previously demonstrated that CD44 mediates tumor cell aggregation, we next examined whether there is a regulatory correlation between CD44 and ICAM1 in tumor clustering." (PMID 34381029, 2021). "Moreover, CD44’s pivotal role in epithelial-mesenchymal transition has a significant impact on tumor progression." (PMID 34599251, 2021). "Additionally, it is possible that CD44+CD133+ tumor-initiating cells from primary xenografts have an enhanced ability to respond to tumor microenvironmental signals via dynamic interactions with their microenvironment in secondary xenografts." (PMID 33994850, 2021). "Similarly, compared to Bevacizumab group, the percentage of CD44+ cells decreased significantly in MDA-MB-231/MDA-MB-468 tumor tissues of Bevacizumab + SHH002-hu1 group (MDA-MB-231: **p < 0.01, MDA-MB-468: **p < 0.01)." (PMID 33436039, 2021). "On the other hand, the liver-abundant miR-192-5p is a tumor suppressor (TS) miRNA strictly associated with cancer stem cells isolated from HCC specimens, resulting in downregulated EpCAM+, CD44+, CD90+, CD133+, and CD24+ CSC-enriched populations compared to negative ones." (PMID 34572776, 2021). "Accumulation of HA-STS-DOX-Lip was observed into the tumor site only which might be due to CD44 homing and ERP effect." (PMID 35431911, 2021). "Further analysis of the DN population based on CD25 and CD44 expression revealed that in tumor-free thymi, most ALK+ cells were DN3 (CD25+CD44−) and DN4 (CD25−CD44−) stage thymocytes, which correlates with the developmental stages at which Cd4 driven NPM-ALK expression was induced." (PMID 33310759, 2021). "Therefore, we modified chitosan oligosaccharide on the surface of liposomes to target CD44-positive tumor cells." (PMID 34011362, 2021). "CD44 in breast CSCs also played a pivotal role in the regulation of tumour cell proliferation, invasion and migration by modulating the levels of c-Src, a master regulator of the MAPK, PI3K, and STAT3 signalling pathways, via the inhibition of c-Jun and degradation by AKT/GSK-3β signalling." (PMID 34944493, 2021). "However, the expression of the NK cell inhibitory ligand HLA-E exhibited the opposite pattern, with lower expression in MDA-MB-231 tumor tissue than in RT-R-MDA-MB-231 or CD24−/low/CD44+ tumor tissue." (PMID 34502547, 2021). "In mouse homograft models, CD44 targeted NIR-PIT suppressed tumor growth and prolonged survival." (PMID 36405499, 2021). "Interestingly, CD90+ CTCs express higher levels of CD44 than those cells located within the primary tumor, suggesting increased tumor aggressiveness." (PMID 34884878, 2021). "Multiple mechanisms that regulate the adhesion step of this process have been identified, including interactions between tumor cell CD44 and mesothelial fibronectin, tumor cell β1 integrins and mesothelial extracellular matrix, and tumor cell CD24 and mesothelial P-selectin." (PMID 34396026, 2021). "Analysis of dendrimers used against tumor cells overexpressing CD44." (PMID 35431911, 2021). "As expected, PBNs (in green) were localized in tumor cells revealed by a human CD44 antibody (red)." (PMID 34069377, 2021).